EGF (epidermal growth factor)
Diseases named in the same sentence as EGF in open-access papers (continued):
Sharing a sentence is not in itself a finding about the gene and the disease.
cancer (continued). "In contrast, perivascular TAM are migratory, are not able to ingest dextran, have a less pronounced M2-profile and produce epidermal growth factor (EGF), which attracts M-CSF-producing cancer cells, resulting in migration and intravasation of cancer cells." (PMID 25339957, 2014). "A growing body of evidence has demonstrated that EGF mediates a variety of cellular events, including cancer cell progression and metastasis." (PMID 25122478, 2014). "The contribution of MMPs and EGF “like” ligands to carcinogenesis and cancer progression is well known." (PMID 25249545, 2014). "We then attempted to deduce the signaling network regulating cell migration in each cancer cell line based on the chemosensitivity profiles obtained on the expression status of EGF-induced signaling molecules." (PMID 24820097, 2014). "In conclusion, the effects of EGF on carcinoma cell lines studied to date are consistent with the following basic scheme: EGF → VGSC upregulation (transcriptional and functional) → increased metastatic cell behaviours." (PMID 24493753, 2014). "A similar EGF/M-CSF paracrine interaction with macrophages, resulting in enhanced cancer cell invasion as reported for murine carcinoma cells, was confirmed in a mouse xenograft model of human breast tumor derived cancer cells." (PMID 25339957, 2014). "Hereby, M-CSF produced by carcinoma cells promotes the expression of EGF by macrophages, which in turn promotes the formation of elongated protrusions and cell invasion by carcinoma cells." (PMID 25339957, 2014). "Both Casodex and S1 peptide also prevent DNA synthesis and migration triggered by EGF in various human cancer-derived cells (prostate, breast, colon and pancreas) that express AR." (PMID 24130806, 2013). "AR or AR/Src blockade by Casodex or S1 peptide impairs the biological responses challenged by EGF in these cancer cells." (PMID 24130806, 2013). "To clarify the role of EGF in the regulation of IL-1β expression, we assessed the gene expression and promoter activity of IL-1β in EGF-treated cancer cell lines, such as TU183, CA922, SCC25, SCC4, and A431 cells." (PMID 23383347, 2013). "Treatment of cells with 2 μM AZA1 for 24 h significantly reduced cancer cell migration by 59.6 ±12% (22Rv1 cells; p<0.001), 56.8 ±18.8% (DU 145 cells; p<0.001) and 57.3 ±16.1% (PC-3 cells; p<0.001) compared to EGF-stimulated cancer cells." (PMID 24040362, 2013). "Our data show that 22Rv1 cancer cell growth is stimulated by EGF and tyrosine kinase receptors contribute to the androgen-independent proliferation of these cells." (PMID 24040362, 2013). "EGF-stimulation significantly increased cancer cell migration in 22Rv1, DU 145 and PC-3 cells (p<0.001)." (PMID 24040362, 2013). "Throughout the past decade, targeted treatment of cancer has mainly focused on the epidermal growth factor (EGF) pathway." (PMID 23420529, 2013). "This supports a prominent role for these miRNA in modulating the effects of EGF on cancer-related cellular processes." (PMID 23724959, 2013). "Oral CSC-like cells can also be isolated from OSCC using a sphere-formation assay by cultivating the cancer cells in serum-free medium with growth factors such as basic fibroblast growth factor (bFGF) and epidermal growth factor (EGF)." (PMID 24423398, 2013). "It is crucial to determine the manner in which EGF-induced IL-1β regulates cancer cells to escape from cisplatin-induced cytotoxicity." (PMID 23383347, 2013). "The release of factors stimulating proliferation of cancer cells, including epidermal growth factor (EGF), platelet-derived growth factor (PDGF), and insulin-like growth factor 1 (IGF-1), is seen as another mechanism." (PMID 24363760, 2013). "The use of anti-cancer target agents is increasing, such as the anti-cancer target drugs blocking the EGF/EGFR system." (PMID 24127898, 2013). "In the Center of Molecular Immunology, a cancer vaccine is produced (CIMAvax® EGF) that blocks the binding of EGF to its receptor." (PMID 24127898, 2013).
cancer (continued). "Together with the additionally released M2-type cytokines (e.g., VEGF, PDGF and EGF), this mechanism can augment the original cancer-promoting effect of the COX-2+ TAMs." (PMID 24324582, 2013). "Polyadenylation is known to be involved in mRNA stability, while EGF signalling has been shown to promote cancer cell proliferation and to enhance mammosphere formation." (PMID 23445407, 2013). "Our results identified a new mechanism of action for indomethacin: inhibition of EGF-mediated calcium signals that is a key determinant of cancer cell migration." (PMID 23736792, 2013). "Administration of anti-EGF or optimized anti-Her2/ErbB2 monoclonal antibody (Herceptin/Trastuzumab) are the most widely used—but also very expensive—inhibitors of EGF signaling for the treatment of cancer." (PMID 23531534, 2013). "EGF signaling provides cancer cells with increased pro-survival responses and deregulated activity of this network leads to diverse types of tumors." (PMID 23724959, 2013). "We have selected examples of the application of aptamers in two intensively studied signaling cascades relevant to embryogenesis, as well as cancers of different histo-pathological classes, i.e., epidermal growth factor (EGF) and Wnt signaling." (PMID 23531534, 2013). "By targeting EGF survival pathways, cancer cells can be forced to undergo apoptosis or become sensitive to radiation or chemotherapy." (PMID 23724959, 2013). "Many reports suggest that EGF and EGFR are critical in cancer progression and their gene polymorphisms are correlated with susceptibility to GC." (PMID 24454509, 2013). "EGF induces the invasion and metastasis of cancer cells and the EGF receptor is over-expressed in a number of human malignancies such as cancers of the lung, brain, breast and bladder." (PMID 23374291, 2013). "The level of phospho-AKT, which was found to be increased in HGF/EGF-stimulated cells after treatment with cetuximab alone reverted back to basal untreated values in the presence of MetHer1 in five cancer cell lines of different tissue origins." (PMID 23812422, 2013). "ERBB4 encodes an epidermal growth factor RTK subfamily member that regulates several cellular processes and plays an important role in cancer." (PMID 23967248, 2013). "Consistent with this, our previous study also observed increased calcium signals evoked by EGF in A431 cancer cells." (PMID 23800047, 2013). "In the cluster of genes that were largely differentially expressed (FDR < 0.05, Student’s t-test) we found prominent cancer-related genes such as EGF." (PMID 23537212, 2013). "The present data have shown that PKG II inhibits EGF/EGFR-induced proliferation and migration and associated signal transduction of MAPK-mediated pathways of cancer cells." (PMID 24273605, 2013). "Although HH- as well as EGF-mediated signaling have been intensely studied, the details of how signals derived from HH or EGF are integrated at the molecular level still needs to be clarified for distinct cell types, and in different cancer entities." (PMID 23762360, 2013). "EGF is an important regulator of cell survival, and in numerous types of cancer, including breast, prostate, pancreas, colorectal, lung and head and neck, an increase in EGF and ErbB, a member of the EGF receptor family, has been demonstrated." (PMID 24137467, 2013). "This aberrant alteration of the receptor family members on cell surfaces can regulate their endocytosis and lead to the altered binding of ligands (e.g., EGF), which consequently affects the cancer signaling pathways mediated by these receptors." (PMID 24009699, 2013). "In fact, CSC-like cells enriched with serum-free medium containing bFGF and EGF mirror the phenotype and genotype of primary tumors more closely than do cancer cell lines cultured in complete serum medium." (PMID 24423398, 2013).
cancer (continued). "Treatment with AZA1 at 2, 5 and 10 μM significantly reduced the relative expression ratio of F- to G-actin in all three cell lines after 24 h compared to EGF-stimulated cancer cells (p<0.01) and control cells (p<0.05)." (PMID 24040362, 2013). "Increased ROS induced by some factors such as growth factor EGF played an important role in cell survival, proliferation, anti-apoptosis, invasion and metastasis, and angiogenesis in cancer cells." (PMID 23750203, 2013). "Factors that stimulate cancer cell growth include the epidermal growth factor (EGF), vascular endothelial growth factor (VEGF) and platelet-derived growth factor (PDGF)." (PMID 23325049, 2013). "In such cells, we unravel the generalized involvement of the beta-catenin-driven machinery in the stabilization of EGF-induced mRNAs, including the cancer stem cell regulator IL6." (PMID 24260469, 2013). "The major finding of this report is that the efficacy of Photofrin-mediated PDT against cancer cells can be enhanced by a highly selective destruction of GRP78 with a targeted subtilase cytotoxin EGF-SubA." (PMID 23887632, 2013). "EGFR is known to be activated under hypoxia and EGF is a well-known growth factor involved in cancer progression." (PMID 23405166, 2013). "These values propose EGF-NIR as a suitable imaging agent for carcinoma visualization using NIR endoscopy, in which high SBRs are required." (PMID 23857061, 2013). "MDA-MB-231 cells were treated with EGF which stimulates the formation of invadopodia in carcinoma cells." (PMID 24072600, 2013). "TGFβ activates Ras, which is required for cell dissociation and spreading during the EGF-induced EMT of the in vitro NBT-II rat carcinoma cell line." (PMID 24009602, 2013). "Validation of EGF-NIR binding properties was performed using monolayers of A431 carcinoma cells expressing high levels of EGFR." (PMID 23857061, 2013). "Over expression of EGFR and altered EGF signaling are common features in a variety of human cancers." (PMID 23185433, 2012). "Many cancer treatments rely on inhibition of epidermal growth factor (EGF)-induced cellular responses." (PMID 25586035, 2012). "Specific inhibition of EGF receptors (EGFR) abolishes cytoskeleton remodeling and migration of cancer cells in response to EGF." (PMID 22701712, 2012). "Several reports showed relation between circulating EGF and patient treatment outcomes in different types of cancers." (PMID 22623992, 2012). "ERK1/2 is activated by MEK1/2, and we confirmed that the inhibition of ERK1/2 signaling using the MEK1/2 inhibitor, U0126, or ERK1/2 siRNA significantly attenuated EGF-induced cancer cell migration and invasion in a dose-dependent manner." (PMID 23083134, 2012). "Targeting its primary mediator, the chaperone protein GRP78, through specific, proteolytic cleavage with the immunotoxin EGF-SubA represents a novel and promising multi-targeted approach to cancer therapy." (PMID 23284962, 2012). "In our system, HepG2 cancer cell migration rate was accelerated after EGF treatment compared with that of the control, but cell proliferation was not altered." (PMID 22701712, 2012). "For example, photoactivation of cofilin in cancer cells induces crawling in the direction of activation; cofilin is also required for EGF-stimulated lamellipodium extension." (PMID 22359556, 2012). "This is due to the fact that an over expression of EGF factors was detected in 75% of cancer patients." (PMID 24558562, 2012). "Cells were cultured in absence of exogenous growth factors, exposing them to either hypoxia and to neutralizing antibodies targeting growth factors that are frequently deregulated in human cancers, including EGF, FGF-2, IGF-I, PDGF-BB, and VEGF-A." (PMID 23144690, 2012). "Consistent with previous results in other cancer cell lines, EGF increased IBDC cell migration and invasion via a mechanism regulated by ERK1/2." (PMID 23083134, 2012).
cancer (continued). "Our results indicated that Arf6 plays an essential role in cancer cell migration during EGF stimulation." (PMID 22701712, 2012). "Sb prevented cancer cell colony formation, reduced EGF-mediated cell proliferation, and increased apoptosis." (PMID 23173670, 2012). "We also show that mammosphere culture consistently generated stem-like cancer cells solely as a result of the EGF and bFGF cytokines in the mammosphere media mediating EMT." (PMID 22134360, 2012). "EGF stimulation increases barbed end density and leading edge actin polymerization in carcinoma cells." (PMID 22359556, 2012). "We previously showed that EGF and other growth factors induce human carcinoma cell invasion and metastasis mediated by integrin αvβ5 that is prevented by Src blockade." (PMID 22586492, 2012). "In this study, we have identified signaling events that are coordinated by epidermal growth factor (EGF) and a specific integrin to regulate the invasive behavior of human carcinoma cells." (PMID 22586492, 2012). "Among the growth factors, high expression of EGF is related to differentiation and invasion by the cancer cells." (PMID 22187659, 2011). "We use this robust gene list to build higher order networks of gene interaction by interconnecting associated networks, supporting and extending the important role of the EGF signaling pathway in cancer." (PMID 21699700, 2011). "Phosphatidylinositol phosphate kinase type Iγ (PIPKIγ) binds talin and is required for focal adhesion formation in EGF-stimulated cells, but its role in regulating focal adhesion dynamics and cancer invasion is poorly understood." (PMID 21931851, 2011). "It has been reported that cancer stem-like cells can be cultured in suspension to generate floating spheroid-like bodies (SB) under serum-free medium with bFGF and EGF." (PMID 20936121, 2011). "PMN-MDSC were found to express Hepatocyte Growth Factor (HGF) and Transforming Growth Factor-β1 (TGF-β1), while cancer cells were the main source of Epidermal Growth Factor (EGF)." (PMID 21980263, 2011). "The apoptotic signaling pathway is inactivated in most cancer cells, including a group of proteases such as caspase-8 and caspase-3 that cross-talk with EGF survival signaling network." (PMID 21617769, 2011). "Similar to estradiol, it is known that cells stimulated by EGF induce voltage-gated K+ ion channel opening in both normal and cancer cells, thus providing an underpinning of the mechanism of action of GIP-8." (PMID 24212829, 2011). "EGF-dependent signaling pathways are often dysfunctional in cancer, and targeted therapies that block EGF signaling have been successful in treating tumors." (PMID 21699700, 2011). "Via direct transcriptional activation, ΔNp63α leads to the up-regulation of epidermal growth factor receptor (EGFR) and 14-3-3σ, sensitizing cancer cells to EGF and enhancing their oncogenic potential." (PMID 22053213, 2011). "Among the top molecular and cellular categories, we observed the presence of the most common functions related to EGF signaling such as cell death, cell growth and proliferation, being cancer the top disease." (PMID 21699700, 2011). "CimaVax-EGF is a therapeutic cancer vaccine composed by human recombinant Epidermal Growth Factor (EGF) conjugated to a carrier protein, P64K from Neisseria Meningitides." (PMID 22024351, 2011). "The active ingredient is the epidermal growth factor (EGF), a protein which is considered a biomarker of uncontrolled cancer and cell proliferation." (PMID 23198109, 2011). "A thorough understanding of the genes that can be modulated by EGF and all the interactions is critical for success on rationally designed cancer treatments." (PMID 21699700, 2011). "The aim of this study was to provide new information on the intricate interaction pattern of EGF and EGFR by comparing the kinetics and the affinity of the 125I-EGF-EGFR interaction in four cancer cell lines." (PMID 21304974, 2011).
cancer (continued). "We and others previously reported that EGF is capable of promoting cancer cell growth through JNK activation." (PMID 22053213, 2011). "Because of the high prevalence of EGFR overexpression in carcinomas, inhibitors of epidermal growth factor (EGF) signaling are potential therapeutic agents." (PMID 21829460, 2011). "EGF modulates the growth and differentiation of various cancer cells, as well as normal epithelial cells, and is excreted through human saliva." (PMID 20429940, 2010). "Survivin, an oncofetal protein with both pro-proliferative and anti-apoptotic properties, is a known transcriptional target of both IGF-1 and EGF in cancer cells." (PMID 20807437, 2010). "EGF and CSF-1 are shown to stimulate invadopodia formation in cancer cells and podosome formation in macrophages, respectively." (PMID 21307399, 2010). "The first description of STAT3 in 1994 raised suspicion in the direction of cancer because IL-6 and EGF, already recognized to have cancer connections, were the originally recognized ligands that activated the STAT3 homodimer." (PMID 21149895, 2010). "The anti-nociceptive function of EGF is an intriguing result in the context of tissue damage but also for understanding pain resulting from EGF-receptor block during cancer therapy." (PMID 21187008, 2010). "Okamoto and colleagues showed that long-term EGF treatment reduced expression of Cav-1 in cancer cells; and subsequently up-regulated snail and down-regulated E-cadherin expression." (PMID 20540763, 2010). "Stimulation of cultured cancer cells with EGF increases invasion and motility and modulates cell adhesion to extracellular matrix components in vitro and in vivo." (PMID 19144191, 2009). "Multiple growth factors such as IGF-1, VEGF, and EGF facilitate the development and progression of cancer by activating PI3K pathway leading to cell survival and therapeutic resistance." (PMID 19891769, 2009). "Several growth factor/hormone signaling pathways that are associated with cancer including fibroblast growth factor (FGF), epidermal growth factor (EGF) and insulin can modulate IRS-1 and IRS-2 expression levels." (PMID 19534786, 2009). "Cancers that produce abnormal amounts of EGF, known as epidermal growth factor (EGF)-overexpressing cancers, have, along with other types of cancers, drawn enormous expense for treatment." (PMID 19816581, 2009). "It has been reported that cancer stem-like cells can be cultured in suspension to generate floating spheroid-like bodies (SB) under serum-free medium with bFGF & EGF." (PMID 18612434, 2008). "Recent evidence indicates that EGF can enhance the Src localization and activation at lipid rafts to regulate cancer development." (PMID 18711637, 2008). "Secreted factors such as CCN proteins, EGF, FGFs and their receptors are often detected in the nucleus of cancer cells." (PMID 17049074, 2006). "Epidermal Growth Factor (EGF) is involved in carcinogenesis and apoptosis sensitivity of cancer cells." (PMID 17014711, 2006). "The existence of these cell line subpopulations will facilitate investigation of EGF-mediated signalling PI3K–Akt in human cancers." (PMID 15870831, 2005). "Heparin-binding epidermal growth factor in peritoneal fluid is generated mainly from cancer cells and peritoneal mesothelial cells, which have the same origin as coelomic epithelium of the NO." (PMID 15827558, 2005). "The effect of gefitinib on cancer cell proliferation under EGF stimulation was investigated in two cell lines (OCUT-2 and ACT-1)." (PMID 15785737, 2005). "In order to use the AP-1-bla ME180 CellSensor as a model system for combining targeted agents against components of a cancer-related pathway, we determined the dose-dependent response of the pathway to EGF stimulation." (PMID 16202132, 2005). "The angiogenic factor vascular endothelial growth factor (VEGF) has been shown to be induced by EGF in various cancer cell lines." (PMID 12618892, 2003).